FAM133B (family with sequence similarity 133 member B)
Synonyms: MGC40405
Tractability: PROTAC: ubiquitination databases record sites on it; its protein half-life has been measured.
Gene: Protein-coding gene on chromosome 7 (92,560,758 to 92,590,409, reverse strand). Ensembl gene ENSG00000234545.
Subcellular location (Human Protein Atlas): Nucleoli; Nucleoplasm
Gene Ontology:
Molecular function: RNA binding
Cellular component: nucleolus; nucleoplasm
Genetic constraint (gnomAD): Loss-of-function variants: 12 observed, 20.84 expected, observed/expected ratio (o/e) 0.58, 90% interval 0.37 to 0.93. The upper end of that interval is the gene's LOEUF score, 0.93, which puts it in group 3 of 6, group 1 being the genes least tolerant of losing a copy. Missense variants: 106 observed, 137.3 expected, observed/expected ratio (o/e) 0.77, 90% interval 0.66 to 0.91. Synonymous variants: 42 observed, 42.55 expected, observed/expected ratio (o/e) 0.99, 90% interval 0.77 to 1.28.
Homologues: Orthologues: chimpanzee FAM133B (100% identical), macaque FAM133B (99% identical), pig FAM133B (96% identical), rabbit FAM133B (96% identical), guinea pig FAM133B (93% identical), dog FAM133B (93% identical), mouse Fam133b (87% identical), rat Fam133b (87% identical), tropical clawed frog fam133b (64% identical), zebrafish fam133b (53% identical). Paralogues in human: FAM133A (81% identical).
Diseases named in the same sentence as FAM133B in open-access papers:
FAM133B is named in the same sentence as 10 diseases in open-access papers, as found by Europe PMC text mining. Sharing a sentence is not in itself a finding about the gene and the disease. The quoted sentences say what the papers report.
nasopharyngeal carcinoma (1 paper, 2020). A carcinoma arising from the nasopharyngeal epithelium. "In this study, we focused on the biological function of the lncRNA FAM133B-2 in the radio-resistance of nasopharyngeal carcinoma." (PMID 32889799, 2020).
FAM133B also shares sentences with these, for which no sentence is quoted: T-cell acute lymphoblastic leukemia (2 papers); acute lymphoblastic leukemia (1); anaplastic astrocytoma (1); angiosarcoma (1); bladder cancers (1); breast carcinoma (1); colon cancer (1); melanoma (1); pancreatic cancer (1).